METTL3 (methyltransferase 3, N6-adenosine-methyltransferase complex catalytic subunit)
Diseases named in the same sentence as METTL3 in open-access papers (continued):
Sharing a sentence is not in itself a finding about the gene and the disease.
colorectal cancer (continued). "For example, the depletion of METTL3 and METTL14 could significantly increase the efficacy of anti-PD-1 therapy against colorectal cancer and melanoma." (PMID 36058919, 2022). "METTL3 stabilized the expressions of HK2 (HGNC:4923) and SLC2A1 (HGNC:11005) in CRC through a m6A-IGF2BP2/3-dependent mechanism to regulate glycolytic pathways and promote colorectal cancer progression." (PMID 35087827, 2021). "Moreover, METTL3 also stimulated the maturation of miR-1246 and thereby downregulated tumor suppressor gene SPRED2, leading to enhanced metastatic capacity of colorectal cancer cells." (PMID 32209098, 2020). "The data strongly suggests that METTL3 may be a tumor-driver gene and promote CRC progression by regulating colorectal cancer glucose metabolism." (PMID 32245489, 2020). "Third, our analysis only described the role of METTL3 and METTL14 in HCC, whether this hypothesis applies to other types of cancer, such as colorectal cancer and glioma, needs further investigations." (PMID 33159022, 2020). "Interestingly, emerging evidence indicated an opposite regulatory role of METTL3 and METTL14 in several cancers, such as glioblastoma, HCC, and colorectal cancer (CRC)." (PMID 33159022, 2020). "Moreover, the deletion of METTL3 or METTL14 increases the infiltration of cytotoxic CD8+ T cells and the secretion of the cytokines IFN-γ, CXCL9, and CXCL10, thereby improving the response to anti-PD-1 therapy in colorectal cancer." (PMID 40986143, 2025). "In colorectal cancer, METTL3 promotes the expression of circ1662 by m6A modification of circ1662 through binding to its flanking strand, while circ1662 can regulate SMAD3 expression by accelerating the nuclear localization of YAP1, which ultimately promotes invasive metastasis of colorectal cancer." (PMID 39289775, 2024). "Therefore, it can be speculated that ALKBH5, METTL3, and FTO may accelerate the growth of colorectal cancer." (PMID 37511932, 2023). "Collectively, our results revealed that METTL3 simultaneously upregulated JAK1 and STAT3 expression in m6A-dependent and -independent manners, which contributed to STAT3 signaling activation, resulting in colorectal cancer proliferation and progression in vitro and in vivo." (PMID 38001065, 2023). "The role of m6A methyltransferases in tumors has been partially reported; for example, METTL3 upregulation promotes the malignant progression of HCC by inhibiting SOCS2 expression through an m6A-dependent mechanism, and METTL14 inhibits proliferation and metastasis in colorectal cancer." (PMID 35494016, 2022). "Moreover, previous studies showed that METTL3 could elevate the stability of SOX2 by increasing its m6A level, thus contributing to the progression of glioma and colorectal cancer." (PMID 35467477, 2022). "In colorectal cancer, the lack of METTL3 or METTL14 increases cytotoxic tumor-infiltrating CD8+ T cells; enhances the production of interferon- (IFN-) γ, CXCL9, and CXCL10; and promotes the recruitment of CD8+ and CD4+ effector T cells that inhibit tumor growth." (PMID 34858499, 2021). "Previous studies have shown that METTL3 methylated SOX2 transcripts, subsequently recognized by the specific m6A “reader” and insulin-like growth factor 2 mRNA-binding protein 2 (IGF2BP2), to maintain SOX2 stability and promote colorectal carcinoma progression." (PMID 34858987, 2021). "Similarly, the overexpression of METTL3 in colorectal cancer leads to abnormal m6A modification, and further promotes tumor progression and metastasis via its targets SOX2 and the METTL3/miR-1246/Sprouty-related EVH1 domain containing 2 (SPRED2) axis, respectively." (PMID 32709063, 2020).
hepatocellular carcinoma (218 papers, 2017 to 2026). A malignant tumor that arises from hepatocytes. "The effects of HSC-specific METTL3 deficiency on HCC were analyzed by orthotopically implanting hepatoma cells into the fibrotic mouse livers, as well as through direct and indirect co-culture systems." (PMID 42030359, 2026). "Lastly, The pro-proliferative effect of METTL3 on hepatocellular carcinoma was mechanistically linked to IRF1/c-Src axis activation, as evidenced by our experimental data." (PMID 40612868, 2025). "Previous studies have shown that YTHDF1 and METTL3 upregulation is associated with poor survival in hepatocellular cancer." (PMID 38436011, 2024). "The depletion of METTL3, a primary m6A methyltransferase, under hypoxia activates autophagy-associated pathways in cultured hepatocellular carcinoma cells." (PMID 36203590, 2022). "METTL3 overexpression is associated with a poor prognosis in patients with hepatocellular carcinoma." (PMID 35456475, 2022). "High METTL3 expression has been associated with poor prognosis of hepatocellular carcinoma (HCC) patients." (PMID 31847302, 2019). "Besides CRC, METTL3-controlled methylation modification of circRNAs has been implicated in pancreatic ductal adenocarcinoma, hepatocellular carcinoma, and non-small cell lung cancer, indicating the potential to target METTL3 in cancer treatments." (PMID 38877514, 2024). "Analysis of the TCGA-liver hepatocellular carcinoma (LIHC) dataset revealed that METTL3 was upregulated in HCC patients with primary tumors compared with normal tissues, and higher METTL3 levels were linked to poorer overall survival in HCC patients." (PMID 39910904, 2025). "For instance, METTL3 is associated with poor prognosis in hepatocellular carcinoma (HCC) patients and promotes HCC cell proliferation through YTHDF2-mediated silencing of SOCS2 transcription." (PMID 38970366, 2024). "METTL3 is up-regulated in human hepatocellular carcinoma (HCC) and is associated with poor prognosis in patients with HCC." (PMID 39872957, 2023). "The current study was aimed to explore the function and underlying mechanism of METTL3 in hepatocellular carcinoma (HCC)." (PMID 32068977, 2020). "In hepatocellular carcinoma (HCC), METTL14 downregulation is associated with tumor metastasis, but METTL3 enhances the invasive ability of HCC cells." (PMID 29061143, 2017). "Similar to the effects of METTL3 deficiency, BMP10 knockdown also promoted hepatoma cell growth, whereas recombinant BMP10 (rBMP10) inhibited it." (PMID 42030359, 2026). "In this study, we observed that T186/S192/S193 O-GlcNAcylation of METTL3 significantly promotes the proliferation, invasion, and migration of hepatoma cells in vitro and in vivo." (PMID 40651967, 2025). "METTL3 O-GlcNAcylation elevated m6A levels in hepatoma cells by enhancing its stability and interaction with WTAP." (PMID 40651967, 2025). "Current evidence suggests that WTAP regulates ferroptosis in hepatoma cells, which recruits METTL3 and METTL14, promoting the m6A methyltransferase to bind with RNA." (PMID 39744575, 2025). "SUMOylation of METTL3 has been shown to accelerate the progression of hepatocellular carcinoma (HCC) by repressing its m6A methyltransferase activity." (PMID 40651967, 2025). "Specifically, METTL3 drives oxaliplatin resistance in hepatocellular carcinoma by activating the G6PD-dependent pentose phosphate pathway." (PMID 40986143, 2025). "While the overexpression of METTL3, a key m6A methyltransferase, boosts sorafenib sensitivity in hepatocellular carcinoma by stabilizing FOXO3 mRNA via m6A methylation." (PMID 40533443, 2025).
hepatocellular carcinoma (continued). "Transwell and wound-healing assays indicated that METTL3 knockdown substantially decreased the migratory and invasive potential of hepatoma cells." (PMID 40651967, 2025). "Our findings revealed that METTL3 upregulates SRC expression in hepatocellular carcinoma through IRF1-dependent regulation." (PMID 40612868, 2025). "For example, METTL3, the catalytic core component of the m6A methyltransferase complex, is frequently upregulated in advanced cancers such as lung adenocarcinoma, hepatocellular carcinoma, pancreatic cancer, and colorectal carcinoma." (PMID 41301491, 2025). "RIP-qPCR analysis confirmed a direct interaction between IGF2BP3 and MCM10 mRNA in hepatoma cells, with METTL3-WT interacting stronger than METTL3-3A." (PMID 40651967, 2025). "In conclusion, our study highlights the suppressive role of METTL3 in the early stages of hepatocellular carcinoma occurrence through its regulation of ER stress pathways." (PMID 40103332, 2025). "O-GlcNAcylation of METTL3 at Thr186/Ser192/Ser193 markedly enhanced hepatoma cell proliferation and metastasis." (PMID 40651967, 2025). "Specifically, METTL3 is upregulated in hepatocellular carcinoma, and its knockdown represses cell invasion and migration while promotes apoptosis." (PMID 40986143, 2025). "METTL3 is frequently upregulated in hepatocellular carcinoma patients, and the upregulated METTL3 inhibits the expression of tumor suppressor SOCS2 through m6A methylation and promotes the development of hepatocellular carcinoma." (PMID 39006762, 2024). "Another study conducted in hepatocellular carcinoma cells reported that METTL3 also had a binding relationship with HIF-1α mRNA to promote the m6A modification and expression of HIF-1α." (PMID 38233403, 2024). "In terms of chemotherapy resistance, a study found that significant downregulation of METTL3 in sorafenib-resistant hepatocellular carcinoma activated autophagy-related pathways and promoted the expression of sorafenib-resistant and angiogenic genes." (PMID 38576024, 2024). "In hepatocellular carcinoma, increased METTL3 expression enhances chemoresistance by m6A modification and overexpression of lncRNA DUXAP8." (PMID 39661414, 2024). "For human liver carcinoma HepG2 cells with different bile acids, the results showed that the mRNA m6A writers METTL3 and METTL14 can be down‐regulated by most bile acids, except lithocholic acid." (PMID 38713722, 2024). "Mechanistically, we find that METTL3-mediated m6A modification of abnormal spindle-microcephaly (ASPM) mRNA promoted its expression in hepatocellular carcinoma (LIHC)." (PMID 38166832, 2024). "METTL3/14 expression is elevated in many cancer tissues including BC, AML, glioblastoma (GBM) and hepatocellular carcinoma (HCC) and is closely associated with cancer cell proliferation." (PMID 38711100, 2024). "For example, the primary m6 A methyltransferase METTL3 is significantly downregulated in human sorafenib-resistant hepatocellular carcinoma." (PMID 37175800, 2023). "In hepatocellular carcinoma, it was shown that METTL3-mediated N6-methyladenosine modification leads to upregulation of LINC00958, which uptakes miR3619-5p and thus upregulates HDGF expression, which facilitates adipogenesis and advancement of HCC." (PMID 38125749, 2023). "NIFK-AS1 is highly expressed in hepatocellular carcinoma (HCC) tissues and cells, and its upregulation is caused by METTL3-dependent m6 A methylation." (PMID 36879187, 2023). "In hepatocellular carcinoma, depletion of METTL3 under hypoxic conditions promoted sorafenib resistance and increased the expression levels of angiogenesis-related genes in cultured hepatoma cells." (PMID 37272931, 2023). "In hepatocellular carcinoma, METTL3 facilitates GLUT1 and GLUT3-mediated glycolysis through the upregulation of HIF1α." (PMID 37996892, 2023). "METTL3, which is highly expressed in hepatocellular carcinoma cells, inhibits RDM1 expression by increasing the m6A modification of its RNA." (PMID 37996892, 2023).
hepatocellular carcinoma (continued). "METTL3 promotes hepatocellular carcinoma proliferation and metastasis by promoting m6A modification at the SOCS2 mRNA 3′ end, resulting in accelerated SOCS2 mRNA degradation." (PMID 38102645, 2023). "METTL3 was highly expressed in hepatocellular carcinoma (HCC), and the expression of ubiquitin-specific protease (USP7) was also increased." (PMID 36835633, 2023). "It has been reported that high METTL3 expression in primary hepatocellular carcinoma (HCC) increases the levels of m6A modification on the tumor suppressor SOCS2." (PMID 36525280, 2023). "Another study indicated that the level of LINC00958, which independently predicted poor overall survival of hepatocellular carcinoma patients, was also elevated by METTL3-mediated m6A modification." (PMID 37365581, 2023). "METTL3 was found to be upregulated in hepatocellular carcinoma (HCC), and METTL3 knockout notably suppressed hepatocellular carcinoma tumorigenicity in vivo." (PMID 35456475, 2022). "METTL3 facilitates hepatocellular carcinoma (HCC) lipogenesis and progression through the m6A modification of LINC00958." (PMID 35912098, 2022). "METTL3 represses the tumor suppressor SOCS2 expression in hepatocellular carcinoma through m6A regulatory mechanisms." (PMID 37529797, 2022). "In hepatocellular carcinoma cells (HCCs), downregulation of METTL3 inhibits glycolytic capacity through the mTOR signalling pathway." (PMID 35159736, 2022). "In hepatocellular carcinoma, METTL3 mediates the m6A modification of LINC00958, leading to the upregulation of LINC00958 through stabilizing its RNA transcript, then upregulates hepatoma-derived growth factor (HDGF) expression." (PMID 35501316, 2022). "The expression of LINC00958 in hepatocellular carcinoma was also influenced by METTL3 in an N6 methylation-dependent manner." (PMID 35223488, 2022). "It is also reported that METTL3 overexpression promotes the proliferation and migration of hepatocellular carcinoma cells." (PMID 35813476, 2022). "Recent works found that m6A modification involves the regulation of hepatocellular carcinoma through METTL3 and METTL14." (PMID 36406135, 2022). "In hepatocellular carcinoma and glioblastoma, several reports have revealed the consistent oncogenic roles of METTL3 and METTL14 in these two cancer types." (PMID 36360287, 2022). "In human hepatocellular carcinoma, METTL3 is frequently up-regulated and can regulate the expression of SOCS2 through an m6A-YTHDF2-dependent mechanism." (PMID 35794583, 2022). "Knockdown of METTL3 can reduce hepatocellular carcinoma cell proliferation, migration, and colony formation, and more interestingly, knockout of METTL3 remarkably suppresses tumorigenicity and lung metastasis." (PMID 33490266, 2021). "Overexpression of METTL3 significantly promoted tumorigenesis and metastasis of hepatocellular carcinoma, mostly through regulation of SOCS2 expression by an m6qa- and YTHDF2-dependent mechanisms." (PMID 33692753, 2021). "In hepatocellular carcinoma, METTL3-mediated m6A modification stabilizes the lncRNA LINC00958 transcript to increase the levels of hepatoma-derived growth factor, thus facilitating tumor growth." (PMID 34721523, 2021). "In patients with hepatocellular carcinoma, upregulation of METTL3 and YTHDF expression decreases patient survival." (PMID 34660577, 2021). "For instance, high expression of METTL3, an m6A methyltransferase, has been reported to be able to facilitate the proliferation and progression of hepatocellular carcinoma, colorectal cancer, and BLCA cells." (PMID 34802433, 2021). "Another component in m6A methyltransferase enzymes, KIAA1429 and its circKIAA1429 were also highly expressed and promoted hepatocellular carcinoma advancement 26, 44, showing the similar mode as METTL3 and circMETTL3 in breast cancer." (PMID 33867838, 2021).
hepatocellular carcinoma (continued). "Secondly, in hepatocellular carcinoma, METTL3 overexpression then inhibited the expression of suppressor of cytokine signaling factor 2 (SOCS2) through an m6A-YTHDF2-dependent mechanism, which ultimately promoted tumor growth." (PMID 34660577, 2021). "METTL3 is overexpressed in hepatocellular carcinoma tissues; knockdown of METTL3 significantly reduced liver cancer cell proliferation, migration, and colony formation in vitro, and remarkably suppressed liver cancer tumorigenicity and lung metastasis in vivo." (PMID 33795529, 2021). "Previously, upregulated expression of METTL3 has been observed in human hepatocellular carcinoma and multiple solid tumors." (PMID 33490266, 2021). "For instance, the upregulated expression of METTL3 in hepatocellular carcinoma is positively related to poor prognosis, while METTL3-mediated m6A modification led to epigenetic silencing of SOCS2 via an m6A-YTHDF2-dependent mechanism." (PMID 35047491, 2021). "In hepatocellular carcinoma, METTL3 knockdown induces the expression of some angiogenic biomarkers and increases the formation of tubes, indicating that METTL3 inhibits angiogenesis." (PMID 34869344, 2021). "METTL3 was also recently reported to be vital for the progression of hepatocellular cancer, leukaemia, as well as malignant glioma through regulating a diverse assay of downstream target genes." (PMID 33749070, 2021). "This article is the first to elucidate the relationship between METTL3 and glycometabolism in hepatocellular carcinoma, which provides new insight into the role of m6A‐related genes in hepatocellular caricnoma." (PMID 32068977, 2020). "Some data show that METTL3 is related to abnormal glucose metabolism and mTOR signaling pathway thereby is directly involved in the regulation of glycolytic activity in hepatocellular carcinoma." (PMID 33552994, 2020). "Loss of RAD52 motif 1 (RDM1), induced by methyltransferase‐like 3 (METTL3)‐mediated m6A modification, correlates with unfavorable clinical outcomes, promotes hepatocellular carcinoma (HCC) cell growth, and induces G2/M cell cycle arrest." (PMID 31670863, 2020). "METTL3 was conspicuously upregulated in hepatocellular carcinoma (HCC) and consequently promoted proliferation and metastasis of HCC via silencing of tumor suppressor SOCS2." (PMID 32111213, 2020). "More importantly, suppressor of cytokine signaling 2 (SOCS2) was identified as a target of METTL3-mediated m6A modification in hepatocellular carcinoma." (PMID 32709063, 2020). "METTL3 is also an unfavorable prognostic factor in hepatocellular carcinoma, and knockdown of METTL3 suppressed hepatocellular carcinoma cell proliferation, colony formation, and migration in vitro." (PMID 32709063, 2020). "For instance, METTL3 is reported as an oncogene for lung adenocarcinoma, glioblastoma and hepatocellular carcinoma, whereas we found decreased METTL3 expression in BC." (PMID 30953473, 2019). "In a recent study, METTL14 and METTL3 have been demonstrated to be downregulation in hepatocellular carcinoma." (PMID 31429529, 2019). "METTL3 was shown to participate in hepatocellular carcinoma (HCC) progression via mRNA m6A modification." (PMID 31632489, 2019). "The half-life of METTL3-3A was shorter than that of METTL3-WT in hepatoma cells." (PMID 40651967, 2025). "METTL16, an m6A methyltransferase discovered recently, operates independently from the METTL3/14 complex and holds significance in a range of cancers, including hepatocellular carcinoma, pancreatic ductal adenocarcinoma, epithelial ovarian cancer, breast cancer, and cholangiocarcinoma." (PMID 40095756, 2025). "USP5 significantly elevated METTL3 expression and reduced METTL3 ubiquitination in hepatoma cells." (PMID 40651967, 2025). "On the contrary, METTL3 could also sensitizes hepatocellular carcinoma cells to sorafenib by increasing mRNA stability of FOXO3 via m6A modification." (PMID 39309428, 2024).